SOCS1 (suppressor of cytokine signaling 1)
Diseases named in the same sentence as SOCS1 in open-access papers (continued):
Sharing a sentence is not in itself a finding about the gene and the disease.
infection (continued). "Herein we characterized the expression of two prominent members of the SOCS family, SOCS1 and SOCS3, during SG-MCMV infection in cell culture models." (PMID 28182772, 2017). "By contrast, infection of murine embryonic fibroblasts (MEFs) with either productive MCMV or UV-inactivated MCMV significantly stimulates SOCS1 and SOCS3 mRNA expression early after infection." (PMID 28182772, 2017). "SOCS1 and SOCS3 are required together to prevent the normal interplay of these factors, essential to fight infection and for tissue repair, from escalating into uncontrolled activity and rapid inflammation." (PMID 27583437, 2016). "Other important factors in the IFN pathway are the negative regulators SOCS1 and SOCS3, which increased from 12 h post infection." (PMID 26411318, 2015). "Two members of the Flaviviridae family of viruses, dengue virus and West Nile virus, similarly induce SOCS, specifically SOCS1 and SOCS3, and this has been considered as potentially inhibiting the IFN response in these infections." (PMID 26617608, 2015). "It is noteworthy that DENV-2 infection induces a significant SOCS1 increase that peaks at 24 h (40-fold), whereas in IFN-λ1 stimulation and subsequent infection this increase was impaired and reached only 20-fold at 24 h." (PMID 26411318, 2015). "Therefore, although we propose that enhanced viral clearance in SOCS1−/−IFN-γ−/− mice is not due to increased IFN/STAT1 activation at the acute phase of infection, these SOCS1-regulated pathways may contribute to the resolution of inflammation after viral clearance." (PMID 25500584, 2014). "Our data supports such a protective role of SOCS1 and SOCS3 given their much higher levels of expression during late infection phase (45 hpi onward)." (PMID 21901105, 2011). "SOCS1 and SOCS3 are typically induced by coronaviruses in early‐stage infection." (PMID 40844207, 2025). "Additionally, miR-221-5p targeted NF-kappa B inhibitor alpha (NFKBIA) and Suppressor of cytokine signaling 1 (SOCS1), which promoted PEDV infection by inhibiting the production of IFN-β." (PMID 38257818, 2024). "In addition, hyper-responsiveness to the infection and enhanced anti-RGNNV activity were suggested by the lower expression of suppressor of cytokine signaling 1 (SOCS1) and BTK." (PMID 35215144, 2022). "Also, the expression levels of SOCS-1, PKR, and OAS1 mRNA were higher in D3-MDMs than in MDMs when matching infection rate conditions were done (e.g., MDMs MOI 3 vs. D3-MDMs MOI), suggesting a direct effect of VitD3 on the regulation of these genes in D3-MDMs." (PMID 34634046, 2021). "Although there was reduced SOCS1 level in YF-17D infected cells, YF-17D did not elicit high antiviral molecules early in infection and, as a result, YF-17D was able to replicate to significantly higher titres." (PMID 32722523, 2020). "Thus, viruses can inhibit IFNAR signaling through the inhibitory protein SOCS1 through AXL and other TAM receptors, hence evading the innate immune response pathway activated by the TLR receptor and promoting its infection." (PMID 33072096, 2020). "Similarly, the target genes of MERTK activation, the cytokine suppressors SOCS1 and SOCS3, were also increased after P strain infection, in addition to IRF-1, that regulates type I IFN levels, which were higher with C#1 compared with P strain infection." (PMID 31695702, 2019). "PIAS3 and SOCS1, two regulators that had been reported to restrict the expression of STAT3 target genes, showed a significant increase of the expression upon infection." (PMID 31575039, 2019). "In addition to the viruses featured in these reviews, more herpesviruses also are now known to stimulate SOCS1 and/or SOCS3 during in vitro or in vivo infection." (PMID 31031749, 2019). "In epithelial cells and fibroblasts, there is no infection-induced expression of SOCS1, and thus virus replication was consistently reduced in response to IFN-γ." (PMID 30075008, 2018).
infection (continued). "Overexpression of SOCS1 in chIFN-α-stimulated DF-1 led to a relative decrease in expression of interferon-stimulated genes (ISGs; MX1 and IFIT5) and increased viral yield in response to PBG98 infection." (PMID 29235573, 2017). "Therefore, MCMV-related stimulation of SOCS1 and SOCS3 occurred during infection of IC-21 mouse macrophages with the IE2-defective MCMV RM4503, suggesting that IE2 is dispensable for this phenotype." (PMID 28182772, 2017). "As a negative regulator involved in innate immunity, along with induction of kinase activity of IRAK1/4 during infection, IRAK-M interacts with IRAK4 to induce transcription of downstream inhibitors such as A20, IĸBα, SOCS-1 and SHIP, to prevent radical immune pathology of the host." (PMID 28835201, 2017). "In agreement with these mRNA data, immunofluorescent staining of IC-21 macrophages for SOCS1 or SOCS3 revealed robust stimulation of these proteins at 3 hrs following infection with productive MCMV, but not after treatment with UVi-MCMV or media." (PMID 28182772, 2017). "Infection of mice with highly virulent clinical isolates of MTB induced type I IFNs, which led to the up-regulation of SOCS1, SOCS4, SOCS5 and other negative regulators of the JAK/STAT pathway resulting in a decrease of Th1 type cytokines and decreased survival of MTB-infected mice." (PMID 29312162, 2017). "In the liver, FoxO3a−/− mice had significantly reduced expression of various cytokines such as IL-1β, IL-12, TNF and IFN-γ at day 7 post-infection as measured by qRT-PCR; though the expression of SOCS-1 and SOCS-3 were not altered." (PMID 27599659, 2016). "Recently, it has been shown that influenza virus-induced SOCS1 is independent of cytokine at early stages of infection both in vitro and in vivo, remarkably suppresses the activation of STAT1." (PMID 26206138, 2015). "SOCS1 antagonist-treated mice showed no drop in body temperature, while control mice experienced approximately a 5% drop in temperature at days 4–8 post-infection." (PMID 26617608, 2015). "Baseline SOCS1 mRNA levels correlated positively with RV1B release at 48 hours after infection in BECs but did not correlate with RV16 release." (PMID 25630941, 2015). "When HDAC is inhibited, SOCS1 and SOCS3 are acetylated and chromatin is relaxed, permitting virus transcription and replication and anterograde transport and shedding of HSV-1 in a lytic cycle of infection." (PMID 24567732, 2014). "However, in the current study, viral burdens at the early phase of infection (4 dpi) were similar among WT, IFN-γ−/− and SOCS1−/−IFN-γ−/− mice, suggesting an insignificant effect of SOCS1 on direct innate control of viral replication in epithelial cells." (PMID 25500584, 2014). "Moreover, many genes exhibited different levels of expression of the various isoforms under infection with one PRRSV strain vs. the other (PARP14, SOCS1, IFIT1, MX1, IFOTM1, RNASEL, PIKSCD and TLR3)." (PMID 24643046, 2014). "It was observed that the blockade of ERK1/2 and p38 did not significantly affect SOCS1 mRNA expression after 24 h of infection." (PMID 24712747, 2014). "Therefore, SOCS1-enhanced lung injury is consistent with prolonged recruitment of neutrophils in IFN-γ−/− and WT mice during the resolution phase of infection." (PMID 25500584, 2014). "With these data in hand, we demonstrated that direct infection of proinflammatory MDMs with F. tularensis elicited an unpolarized surface phenotype, as indicated by marked downregulation of all eight M1 and M2 markers tested, and showed that this was accompanied by upregulation of IDO and SOCS1." (PMID 40977725, 2025). "From the cytokine profiling of various groups, we can conclude that Peptide8 inhibits the binding of SOCS1 with gp130, restores the phosphorylation of STAT1 and activation of JAK-STAT1 signaling pathway, thereby formation of pro-inflammatory cytokine during infection." (PMID 35011356, 2021).
infection (continued). "As SOCS1 and SOCS3 were induced by H5N1 virus in the initial round of viral replication at 6-h post infection, we next investigated if this cellular event could affect the expression of IFN-β after multiple rounds of influenza virus replication by infecting the cells using MOI of 0.001." (PMID 29475453, 2018). "Meanwhile, anti-inflammatory factors such as TNFAIP3, NFKBIA, NFKBIZ, SOCS1, SOCS3, and IL-10 were elevated, with the reverse trends for the inflammation-inducing genes PPBP and MARCO at 38 hpi, suggesting that the pro- and anti-inflammatory responses might coexist in PAMs during YC-2020 infection." (PMID 36338035, 2022). "Notably, in high‐dose infection (YM = 1), STING‐ and Caspase1‐mediated signalling contributed equally to induce Socs1 expression, but diverse type I IFN production, which may arise from earlier onset time of Socs1 mRNA triggered by STING‐mediated pathway than Casp1‐dependent signalling." (PMID 32885594, 2020). "Unlike UVi-MCMV infection of IC-21 cells, which produced no significant up-regulation of SOCS1 or SOCS3 transcripts during the time points observed in these macrophages, UVi-MCMV infection of MEFs caused significant, albeit transient, stimulation of SOCS1 and SOCS3 mRNA expression at 2 hpi." (PMID 28182772, 2017). "Of interest, expression of SOCS-1 was earlier and faster than that of IFN-λ, suggesting that SOCS-1 expression is cytokine-independent at least at the early stage of infection and SOCS-1 might regulate IFN-λ expression beyond negative feedback regulation to respond the cytokines in vivo." (PMID 24391501, 2014). "However, Julien and coworkers have observed that up-regulation of SOCS-1 and SOCS-3 in IAV-infected cells is IFNAR1-dependent, which does not contradict with our observation, because we found that the culture supernatants at the later stages of infection indeed stimulated SOCS-1 expression." (PMID 24391501, 2014). "Indeed, infections with both gram-positive, gram-negative bacteria as well as Mycobacterium tuberculosis and parasites, such as Leishmania major and the fungus Candida albicans promote SOCS-1 expression to actively suppress the immune response, allowing pathogen replication and immune evasion." (PMID 33690673, 2021). "In agreement with the kinetics pattern of miR-30c-5p and SOCS1 in Vero E6 cells, PEDV infection reduced the levels of miR-30c-5p and increased SOCS1 expression in IPEC-J2 starting at 12 h post-infection (data not shown)." (PMID 32574254, 2020). "In contrast, silencing of SOCS1 and SOCS2, respectively, did not significantly alter the DC phenotype upon infection." (PMID 33023610, 2020). "In yet another demonstration of cell type specificity, SOCS1 mRNA and protein are induced upon MHV-68 infection of mouse BMMs and RAW264.7 mouse macrophages, but not MLE-12 mouse lung epithelial cells, NIH3T3 fibroblasts, or MEF cells." (PMID 31031749, 2019). "Similar results to those seen in BMMs following infection were also seen in Raw264.7 cells compared to MEF and MLE-12 cells, in that MHV-68 infection induced the expression of SOCS1 in Raw264.7 cells but not in MEF and MLE-12 cells." (PMID 30075008, 2018). "That SOCS3, but not SOCS1, is sensitive to GCV treatment suggests divergent or temporally-driven mechanisms for stimulation of these proteins during late infection with MCMV." (PMID 28182772, 2017). "Blockage of STAT pathways therefore does not necessarily preclude the induction of SOCS1 and/or SOCS3 by other cellular or viral mechanisms, even at later times of infection." (PMID 28182772, 2017). "We found that SOCS1 and SOCS3, but not SOCS5, mRNA transcripts are up-regulated at early time points following infection of IC-21 monolayers with SG-MCMV." (PMID 28182772, 2017). "Type I IFN, SOCS-1 and SOCS-3 expression were not detectably different between RSV A2 and RSV mutant infection, but type III IFN secretion was increased in rA2-GC12 and GC4 infected Calu-3 cells." (PMID 28671606, 2017).
infection (continued). "In SOCS-1 knockdown A549 cells, but not the control cells, the level of STAT1 phosphorylation was notably increased during the infection, indicating that SOCS-1 was a direct inhibitor of STAT1 phosphorylation during IAV infection." (PMID 24391501, 2014). "The studies center on SOCS1 and SOCS3 negative regulation of the type I IFN response and ISG15 expression following infection with RSV or RSV mutant viruses lacking the G gene, or NS1 and NS2 gene deletions." (PMID 18851747, 2008). "In these studies, the role of SOCS1 and SOCS3 negative regulation of the type I IFN response and ISG15 expression were evaluated after infection of MLE-15 cells with RSV or RSV mutant viruses lacking the G gene, or having NS1 and NS2 gene deletions." (PMID 18851747, 2008). "At the earlier time points post-infection, we did not observe any overlap with down-regulated mRNAs; however, 27 up-regulated mRNAs were common to all early treatment groups, including TLR3, IFIT5, IFIH1 (MDA5), MX1, RSAD2 (viperin), CMPK2, SOCS1, and SCNN1D." (PMID 38675946, 2024). "We report that infection of IC-21 mouse macrophages with MCMV propagated through the salivary glands of BALB/c mice, but not from tissue culture in C57BL/6 fibroblasts, transiently stimulates SOCS1 and SOCS3 mRNA transcripts, but not SOCS5 mRNA." (PMID 28182772, 2017). "We previously demonstrated that RSV6340 (a wild type virus) infection could induce SOCS-1/-3 and IFN expression, an effect that was severely ablated upon infection with a recombinant virus lacking the G protein (RSV ΔG)." (PMID 28671606, 2017).
bacterial infection (14 papers, 2016 to 2025). "GAS, which causes various systemic diseases induced SOCS1 that participates in the GAS' evasion of host immune responses in murine macrophages by dampening cytokine expression leading to rapid bacterial infection." (PMID 29312162, 2017). "In addition, macrophages deficient in METTL14 or YTHDF1 exhibit impaired SOCS1 induction, leading to increased pro-inflammatory cytokine and chemokine production, which exacerbates responses to bacterial infections." (PMID 39686999, 2024). "Other studies have suggested that m6A methylation of Socs1 is required to suppress inflammatory responses in murine macrophages upon bacterial infection." (PMID 39995976, 2025). "In bacterial infection, Mettl14 depletion blocked m6A methylation of SOCS1, diminishing its RNA stability." (PMID 35598196, 2022). "The increase in METTL14 and the increase in METTL14 mediate the increase in the m6A modification of SOCS1, and the increase in SOCS1 mRNA stability through YTHDF1 is necessary to maintain the negative feedback control of macrophage activation in response to bacterial infection." (PMID 39337381, 2024). "Hence, we validated the expression of miR-30e, which is upregulated during bacterial infections/PAMPs and selected SOCS1 and SOCS3, important negative regulator of innate immune signaling pathways which are significantly targeted by miR-30e." (PMID 33585275, 2020). "Altogether, miR-30e qualifies to combat bacterial replication by enhancing innate immunity via targeting SOCS1 and SOCS3, two crucial negative regulators of innate immune signaling cascade during bacterial infections." (PMID 33585275, 2020). "The most intended target is the interferon responses, mediated by STAT1 and controlled by SOCS1 and SOCS3, which play pivotal roles in the defense against bacterial infections." (PMID 29312162, 2017). "As SOCS1 and SOCS3 play essential roles in response to bacterial infections, they are therefore explicitly targeted for immune evasion." (PMID 29312162, 2017). "However, some studies have confirmed that miRNAs, such as miRNA-30e, can regulate the SOCS1 and SOCS3 genes during bacterial infection." (PMID 38668243, 2024). "SOCS1 and SOCS3 are target genes of STAT1 and STAT3, respectively, and are critical negative regulators of JAK-STAT signaling and thus maintain normal cytokine levels during viral or bacterial infections." (PMID 33968006, 2021). "Taken together, miR-30e targets SOCS1 and SOCS3 significantly which might regulate innate immunity during bacterial infection." (PMID 33585275, 2020). "Therefore, we sought to characterize miR-30e binding with SOCS1 and SOCS3 during bacterial infections." (PMID 33585275, 2020). "Our analysis revealed downregulation of miRNA-150 during bacterial infection may exert broad effects on metabolism (SLCA2A3/GLUT3), cytokine regulation (SOCS1), and cell signaling pathways (MAPK13, IPO8, ACVR1B, RNF146) consistent with the host response to bacterial infection." (PMID 30619110, 2018). "Furthermore, targeting STAT activity that is strictly regulated by SOCS1 and SOCS3 proteins, by inhibiting tyrosine kinases, could allow avoiding the subversion of the innate immune responses during a bacterial infection and therefore represents an attractive antibacterial therapeutic approach." (PMID 29312162, 2017).
inflammation (9 papers, 2016 to 2023). Aberrant reaction of the microcirculation characterized by movement of fluid and leukocytes from the blood into extravascular tissues. "An SOCS1 peptidomimetic has been used to halt the onset and progression of renal inflammation and fibrosis in DN." (PMID 30214448, 2018). "Another argument in favor of the possible role of photoreceptors in retinal inflammation is that opsin-driven SOCS1 overexpression mitigates EAU development." (PMID 28720143, 2017). "Therefore, we propose that the repressive effect of curcumin on JAK/STAT signaling is mediated by SOCS-1 in TNBS-induced intestinal inflammation." (PMID 27544348, 2016).
immune disease (6 papers, 2015 to 2024). "In conclusion, our data suggested that miR-155 downregulation in NK cells of IA patients impaired IFN-γ production by targeting SOCS1, which may contribute to immune dysfunction during CHB infection." (PMID 29018442, 2017).
colorectal (3 papers, 2015 to 2022). "When GLP1 was administered (CD+GLP1+LT), it resulted in higher SOCS1 and SOCS3 expression than in the CD+LT group, and this was accompanied by less liver inflammation, evidenced by decreased levels of liver MPO, MDA, NO production, nitrotyrosine, and plasma vWF." (PMID 31835410, 2019).
hematological malignancies (3 papers, 2015 to 2021). "A large body of literature deals with the investigation of SOCS1 and SOCS3 in malignant diseases especially in the hematopoietic system demonstrating the importance of SOCS1 and SOCS3 in hematological disorders." (PMID 28753604, 2017). "Phenotypically, mutant ASXL1 impairs the BAP1-ASXL1-FOXK1/K2 transcriptional nexus and downregulates TXNIP, VHL, and SOCS1/2, and consequently promotes glucose metabolism and enhances oncogenic HIF-1α and JAK-STAT3 signaling pathways known to be altered in hematological malignancies." (PMID 32683582, 2021).
kidney disease (3 papers, 2018 to 2025).